OR5A2 (olfactory receptor family 5 subfamily A member 2)
Description:
Odorant receptor.
Tractability: Antibody: UniProt places it where antibodies can reach, with medium confidence; UniProt predicts a signal peptide or a membrane-spanning region; its Gene Ontology location is reachable by antibodies, with medium confidence.
Gene: Protein-coding gene on chromosome 11 (59,416,969 to 59,426,413, reverse strand). Ensembl gene ENSG00000172324.
Subcellular location: Cell membrane
Pathways (Reactome):
Sensory Perception: Expression and translocation of olfactory receptors
Gene Ontology:
Molecular function: odorant binding; olfactory receptor activity; G protein-coupled receptor activity
Biological process: sensory perception of smell; detection of chemical stimulus involved in sensory perception of smell; G protein-coupled receptor signaling pathway
Cellular component: plasma membrane; membrane
Genetic constraint (gnomAD): Loss-of-function variants: 0 observed, 0.21 expected, observed/expected ratio (o/e) 0, 90% interval 0 to 1.88. That is too few expected variants to judge how well the gene tolerates losing a copy. Missense variants: 406 observed, 421.41 expected, observed/expected ratio (o/e) 0.96, 90% interval 0.89 to 1.05. Synonymous variants: 155 observed, 159.14 expected, observed/expected ratio (o/e) 0.97, 90% interval 0.85 to 1.11.
Homologues: Orthologues: chimpanzee OR5A2 (98% identical), dog OR5A2 (87% identical), guinea pig OR5A2 (81% identical), rat Or5a21 (79% identical), mouse Or5a21 (78% identical), tropical clawed frog or5f1l1.2 (47% identical), tropical clawed frog or5f1l1.3 (47% identical), tropical clawed frog or5f1l1.1 (46% identical), tropical clawed frog or8a1 (40% identical). Paralogues in human: OR5A1 (63% identical), OR5AN1 (56% identical), OR5AP2 (51% identical), OR9G4 (50% identical), OR5B12 (49% identical), OR5I1 (49% identical), OR5F1 (48% identical), OR5L1 (48% identical), OR8I2 (48% identical), OR9I1 (48% identical), OR5B21 (48% identical), OR5L2 (48% identical), and 84 more.
Diseases named in the same sentence as OR5A2 in open-access papers:
OR5A2 is named in the same sentence as 2 diseases in open-access papers, as found by Europe PMC text mining. Sharing a sentence is not in itself a finding about the gene and the disease.
OR5A2 shares sentences with these, for which no sentence is quoted: cancer (1 paper); tumour (1).